CSN3 (casein kappa)
Description:
Kappa-casein stabilizes micelle formation, preventing casein precipitation in milk.
Synonyms: CSN10; CSNK; CNS10; KCA
Tractability: Antibody: its Gene Ontology location is reachable by antibodies, with high confidence; UniProt places it where antibodies can reach, with medium confidence; UniProt predicts a signal peptide or a membrane-spanning region.
Target class: Secreted protein
Gene: Protein-coding gene on chromosome 4 (70,238,382 to 70,251,474, forward strand). Ensembl gene ENSG00000171209.
Subcellular location: Secreted
Pathways (Reactome):
Transport of small molecules: Miscellaneous transport and binding events
Gene Ontology:
Molecular function: protein binding
Biological process: lactation; protein stabilization
Cellular component: extracellular region
Genetic constraint (gnomAD): Loss-of-function variants: 2 observed, 4.1 expected, observed/expected ratio (o/e) 0.49, 90% interval 0.2 to 1.47. That is too few expected variants to judge how well the gene tolerates losing a copy. Missense variants: 218 observed, 207.93 expected, observed/expected ratio (o/e) 1.05, 90% interval 0.94 to 1.17. Synonymous variants: 73 observed, 74.43 expected, observed/expected ratio (o/e) 0.98, 90% interval 0.81 to 1.19.
Homologues: Orthologues: chimpanzee CSN3 (98% identical), macaque CSN3 (93% identical), dog CSN3 (65% identical), pig CSN3 (58% identical), rabbit CSN3 (53% identical), rat Csn3 (40% identical), mouse Csn3 (38% identical).
Diseases named in the same sentence as CSN3 in open-access papers:
CSN3 is named in the same sentence as 47 diseases in open-access papers, as found by Europe PMC text mining. Sharing a sentence is not in itself a finding about the gene and the disease. The quoted sentences say what the papers report.
diabetes (8 papers, 2012 to 2025). "CSN3 was also identified as a novel candidate genes for type 2-diabetes mellitus (T2-DM) in a genome-wide association scan in the Old Order Amish." (PMID 22536414, 2012). "Other genes, linked to SVD, are CSN3 and HLA-DPB1, which are unique to patients with lacunar stroke, CSN3, which is also associated with coronary disease and diabetes mellitus, and SH3TC1, which is also implicated in Charcot-Marie-Tooth disease." (PMID 35052389, 2021). "Since these are mainly early-onset strokes, the same study showed that higher blood pressure levels were found in subjects with polymorphisms of these genes, while the polymorphisms of other genes, CSN3, HLA-DPB1 and SH3TC1, are associated with cardiovascular diseases and diabetes mellitus." (PMID 35741740, 2022).
glioma (5 papers, 2007 to 2023). A benign or malignant brain and spinal cord tumor that arises from glial cells (astrocytes, oligodendrocytes, ependymal cells). "Thus, the cytotoxicity of VV-GMCSF-Lact against glioma and NB cells results from both VACV genome-encoded factors and modifications to the viral genome by the human CSN3 gene fragment encoding the proapoptotic peptide lactaptin." (PMID 37998351, 2023). "It is noteworthy that viral CSN3 mRNA is the second most important transcript (after VACV H5R) showing a negative correlation with CD50, as it is directly related to the cytotoxic effect of the virus on glioma cells." (PMID 37998351, 2023).
breast cancer (4 papers, 2022 to 2025). A primary or metastatic malignant neoplasm involving the breast. "Among the key genes found in these enriched categories, TPSD1, FABP4, CARTPT, TRH, CSN3, and MMP9 stand out based on previously published data, which suggest their critical roles in cancer progression, including breast cancer." (PMID 40870889, 2025).
Stroke (4 papers, 2012 to 2023). Sudden impairment of blood flow to a part of the brain due to occlusion or rupture of an artery to the brain. "The exomic analyses informed upon by our lacunar stroke GWAS results identified two genes, CSN3 and HLA-DPB1, which appeared to have excess variation in our stroke cases." (PMID 22536414, 2012).
type 2 diabetes (4 papers, 2012 to 2023). "In this study of 124 type 2 diabetic case subjects as compared with 295 control subjects, CSN3 SNP rs3775745 was found to be associated with T2-DM in the Amish (p = 0.002), with this result replicating in a Mexican-American population (p = 0.003)." (PMID 22536414, 2012).
mastitis (3 papers, 2009 to 2026). Inflammation of breast tissue during lactation or postpartum due to an obstructed duct or infection. "The three prioritized genes for both Trait_GWAS and EBV_GWAS datasets (PHGDH, SLC1A4, and CSN3) play relevant roles in biological processes associated with milk production, cheese production, and resistance to mastitis." (PMID 41306553, 2025).
lung carcinoma (2 papers, 2007 to 2022). "In lung cancer, CSN3 knockdown blocks cell cycle progression at G0/G1 phase by upregulating p21 and downregulating CDK4 and cyclin B146." (PMID 35315259, 2022). "CSN3 deletion restrains lung cancer tumor growth by repressing cell cycle progression." (PMID 35315259, 2022).
osteosarcoma (2 papers, 2022 to 2024). A usually aggressive malignant bone-forming mesenchymal neoplasm, predominantly affecting adolescents and young adults. "The silencing of CSN3 also impairs EMT in osteosarcoma cells and prostate cancer." (PMID 35315259, 2022). "Moreover, the CSN3 gene is located on chromosome 17p11.2 ̃p12, an unstable chromosomal region that is frequently amplified in osteosarcomas and multiple myelomas." (PMID 35315259, 2022). "Knockdown of the CSN3 gene has been found to decrease the metastasis of osteosarcoma cells." (PMID 35315259, 2022). "Moreover, knockdown of CSN3 is associated with downregulation of ERK signaling, thereby decreasing the lung metastasis of osteosarcoma cells." (PMID 35315259, 2022). "In addition, CSN3 knockdown downregulates the expression of MAPK signaling; therefore, CSN3 may have an essential role in the metastasis of osteosarcoma cells." (PMID 35315259, 2022).
Alzheimer disease (1 paper, 2025). A progressive, neurodegenerative disease characterized by loss of function and death of nerve cells in several areas of the brain leading to loss of cognitive function such as memory and language. "CSN3 can inhibit ABCA1 degradation by binding to it, while substances such as cadmium, AGEs, and APOE4 differentially regulate ABCA1 stability by affecting ubiquitination or lysosomal function, thereby being associated with pathological processes such as atherosclerosis and Alzheimer’s disease (AD)." (PMID 41303341, 2025).
COVID-19 (1 paper, 2023). A disease caused by infection with severe acute respiratory syndrome coronavirus 2. "On the other hand, the kappa casein (CSN3) content was reduced nearly tenfold in COVID-19 samples when compared to control samples." (PMID 37628421, 2023). "Moreover, according to our data, some nutritional components of human colostrum are reduced in the colostrum of COVID-19 patients, including kappa casein (CSN3)." (PMID 37628421, 2023). "The kappa casein (CSN3) content was reduced nearly tenfold in COVID-19 samples." (PMID 37628421, 2023).
embryonal carcinoma (1 paper, 2013). A non-seminomatous malignant germ cell tumor characterized by the presence of large germ cells with abundant cytoplasm resembling epithelial cells, geographic necrosis, high mitotic activity, and pseudoglandular and pseudopapillary structures formation. "We found that the expression of Csn3 was induced by all-trans retinoic acid (ATRA) during neural differentiation in P19 embryonal carcinoma cells from our study using DNA microarray." (PMID 23613978, 2013).
hepatocellular carcinoma (1 paper, 2017). A malignant tumor that arises from hepatocytes. "We found that knockdown of CSN3 in C2C12 blocks cell cycle progression through S phase, which is in contrast from the work of others who showed that knockdown of CSN3 in hepatocellular carcinoma cells led to cell cycle arrest at (G0/G1)." (PMID 28623958, 2017).
ischemic stroke (1 paper, 2012). A stroke disorder caused by obstruction of blood flow to the brain, due to thrombotic (local blood clot formation) or embolic (due to a blood clot or other material traveling from another site) event. "Additional research will be required to determine if CSN3 variants are truly associated with ischemic stroke risk." (PMID 22536414, 2012).
muscular dystrophies (1 paper, 2017). "Further in vivo characterization of CSN/CSN3 may lead to the discovery of novel therapeutic target of skeletal muscle diseases such as muscular dystrophies." (PMID 28623958, 2017).
cancer (13 papers, 2013 to 2025). A tumor composed of atypical neoplastic, often pleomorphic cells that invade other tissues. "CSN3 is crucial for the maintenance of cell proliferation in mouse embryonic epiblasts and is associated with cancer progression and metastasis." (PMID 35315259, 2022).
tumor (13 papers, 2007 to 2025). "Among epithelial populations, we identified tumor cells (expressing Cd44, Ccnd1, Plau, Krt7), luminal alveolar (AV) cells (expressing Kit, Ehf, Csn3, Ltf), luminal hormone-sensing (HS) cells (expressing Prlr, Esr1, Pgr), and myoepithelial cells (expressing Myh11, Mylk, Myome1)." (PMID 41332581, 2025). "Therefore, targeting CSN3 may be a promising strategy for anti-tumor therapy." (PMID 35315259, 2022). "Of these 7 survival-related genes, CSN3, KRT81, MUC7, and MYH6 has been elucidated to take part in tumor progression." (PMID 33530209, 2021). "Tumor microenvironment related genes ADGRG7, CSN3, CST8, KRT81, MUC7, MYH6, and SEZ6 are valuable predictors for HNSCC patient survival." (PMID 33530209, 2021).
infection (4 papers, 2011 to 2021). The state of being infected such as from the introduction of a foreign agent such as serum, vaccine, antigenic substance or organism. "CSN3 plays a significant role in the small intestine and influences gut functions, including immune stimulation, mineral and trace element absorption, and host defense against infection." (PMID 34573471, 2021). "Moreover, CSN3 prevents infection by disrupting the attachment of pathogens to mucosal cells." (PMID 32059637, 2020). "With respect to Jersey breed, peptides resulting from partial digestion of high abundant proteins such as LALBA, CSN2 and CSN3 in the small intestine may influence gut functions including immune stimulation, mineral and trace element absorption and host defence against infection." (PMID 32059637, 2020). "Two markers of MEC (CSN3, CSN1S2) were also included as positive controls which were expressed at the same level in MFG of uninfected and infected udder, at all time points post infection." (PMID 24521038, 2014). "Since depletion of any of the CSN subunits results in the loss of the complex, it would not be surprising that silencing of CSN3 results in a hindered infection." (PMID 21818318, 2011).
CSN3 also shares sentences with these, for which no sentence is quoted: endothelial dysfunction (6 papers); Hypertension (5); Obesity (5); cardiovascular disease (4); glioblastoma (3); brain tumor (2); Arthritis (1); asthma (1); atherosclerosis (1); blood cancers (1); breast tumour (1); channelopathies (1); Charcot-Marie-Tooth disease (1); chronic myeloid leukemia (1); coronary atherosclerosis (1); coronary disease (1); epilepsy (1); essential hypertension (1); Hyperkalemia (1); irritable bowel syndrome (1); leukemia (1); lung adenocarcinoma (1); lymph node metastases (1); Miscarriage (1); neuroblastoma (1); neurological disorders (1); preeclampsia (1); prostate carcinoma (1); psychiatric disorder (1); Ventricular arrhythmia (1).